GRB2 (growth factor receptor bound protein 2)
Diseases named in the same sentence as GRB2 in open-access papers (continued):
Sharing a sentence is not in itself a finding about the gene and the disease.
cancer (continued). "In addition, Grb2 acts as a major signal transduction molecule that plays a role in multiple downstream cancer signaling pathways." (PMID 34162761, 2021). "Because Grb2 is centrally located in signal transduction and is crucially involved in propagation of oncogenic tyrosine kinase signals to downstream mediators, it is an attractive therapeutic target in cancer." (PMID 32754300, 2020). "Indeed, multiple signaling pathways are associated with cancer metastasis including MAPK (ERK1/2, JNK, p38), PI3K/AKT, NF-κB, TGF-β, chemokine pathways, Grb2 and other adaptor protein pathways, and many others." (PMID 32714407, 2020). "Both in vitro and in cellula experiments confirm that the lead compound successfully interfere with the binding between the C-SH3 domain of Grb2 and a peptide mimicking the 503 to 524 sequence of Gab2 and highlight its capability to inhibit the growth of cancer cell lines." (PMID 33171874, 2020). "The studies showed that ITGB1- and GRB2-assosiated signaling pathways not only take part in proliferation regulation and the induction of different signaling cascades but also extensively participate in the promotion of cancer cell migration-related processes." (PMID 30327774, 2018). "Our data also reveal the presence of high levels of pY160, the monomeric signalling active form of Grb2, in cancer tissue cells and suggest that this could be a marker for proliferative MAPK activation and resulting oncogenic outcome." (PMID 26103942, 2015). "Most importantly, our group have found SUMOylation has been linked to cancer initiation and development, for examples, SUMOylation of tumor suppressors PTEN, Egr1 and oncogenic protein Grb2 regulate tumorigenesis; SUMOylation of RhoGDI (Rho GDP-dissociation inhibitor) enhances cancer cell motility." (PMID 25823821, 2015). "Therefore, we would predict that in tyrosine kinase-driven cancers phosphorylation of Y160 and the resulting dissociation of Grb2 dimers would be capable of inducing cell proliferative and metastatic outcome." (PMID 26103942, 2015). "Grb2 contributes to cancer cell proliferation and migration through RTK pathways." (PMID 26035354, 2015). "Hence, the anti-cancer strategies targeting Grb2 is also focused on the disruption of the Grb2-Sos1 complex by blocking the interaction of Grb2 SH3 domain with Sos1." (PMID 24775912, 2014). "Given that Grb2 acts as an oncogene in most mammalian cancer development, we asked whether SUMOylation of Grb2 is involved in the cellular transformation." (PMID 24775912, 2014). "In this regard, we show that although oncogenic engagement of Grb2 or Shc triggers redundant cancer properties in IECs, these adaptor proteins were proven, through analysis of the impact of their silencing in Tpr-Met-transformed IECs, to be necessary for non-overlapping functions." (PMID 24708867, 2014). "It is therefore anticipated that the Grb2- and Shc-specific docking oncoproteins, and Tpr-Met may prove, upon further analyses, to mediate distinct signaling pathways, and therefore specific cancer processes in IECs." (PMID 24708867, 2014). "Disrupting the interaction of Shc and Grb2 inhibits tumor growth of the xenograft mice, telling that Shc pathway may be served as an ideal cancer therapeutic target." (PMID 23211466, 2012). "Hence, we do not rule out the possibility of p66shc participating in the development of cancers through Grb2-Ras pathway in addition to operating through Eps8-Rac1 pathway." (PMID 20565814, 2010). "However, there are three cancer-related genes (GRB2, GAS6, MLLT6) found in regions of gain at least five times more frequently than lost that are not kinases." (PMID 16457699, 2005). "Hence, understanding the intricate structure and functions of GRB2 provides valuable insights for the medical community to develop targeted therapeutic approaches to treat diseases, particularly those driven by dysregulated signaling pathways, such as cancer." (PMID 38540680, 2024).
cancer (continued). "DNM2 is the main interactor of the ubiquitously expressed adapter Growth factor receptor-bound protein 2 (Grb2) in hepatocarcinoma cells, suggesting that various signal transduction pathways involving Grb2 may be impaired in case of DNM2 deregulation in cancer cells." (PMID 34294140, 2021). "Hence, insulin affecting cancer cell metabolism by downregulating the GRB2 may have key meaning for the planning of novel treatments." (PMID 31719636, 2019). "Interestingly, it was reported that blocking Shc/Grb2 interaction suppressed the growth of B104-1-1 tumours xenografted in nude mice, showing that cancer treatment might also target the adapter proteins." (PMID 25613377, 2015). "Therefore, the mechanistic insight gained from this work might pave the way for developing novel strategies towards cancer therapy, based on stabilizing the formation of Grb2 dimers." (PMID 26103942, 2015). "Vasculogenic mimicry (VM) usually refers to the plasticity of aggressive cancer cells forming de novo vascular networks and VM formation can be used to assess cellular transformation, so next we used the VM assay to confirm the effect of Grb2 SUMOylaiton on the transformation potential." (PMID 24775912, 2014). "Collectively, our results provide novel evidence that signaling pathways engaged by deregulated RTKs in CRC, including those reliant on Grb2 or Shc, may represent important regulators of anoikis resistance in IECs, a process of outmost relevance in cancer metastasis." (PMID 24708867, 2014). "The MBD Try1349 and 1356 provide a docking platform to recruit the Src homology-2 domain, phosphotyrosine-binding domain, and other critical MBD adapter proteins GAB1, GRB2, phospholipase C, and SRC required for activating cancer motility." (PMID 41470892, 2025). "We initially selected three genes (PAK1, RAF1, and GRB2) based on their involvement in critical molecular signaling networks, including the MAPK signaling pathway, proteoglycans in cancer, focal adhesion, and natural killer cell-mediated cytotoxicity." (PMID 40243635, 2025). "For example, in the DLX4 gene module, connections among DLX4, the known cancer gene ABL1, and four candidate AML genes (SP1, FYN, GRB2, and SMAD2) co-occurred in multiple patients." (PMID 39013885, 2024). "Grb2 protein is in the monomer and dimer conversion process, activating and inhibiting MAP kinase, respectively, controlling cancer progression." (PMID 39771106, 2024). "These collective data show that low GRB2 levels enable cGAS/STING activation and immune detection of cancer cells." (PMID 38459011, 2024). "Further research is needed to fully understand the balance between GRB2 and GRB3-3 and their specific roles in establishing Ras signaling in cancer and other disease states." (PMID 38540680, 2024). "SH2B3 bound to JAK2 and SHP2 to repress JAK2/STAT3 and SHP2/Grb2/PI3K/AKT signaling pathways, respectively, resulting in reduced cancer cell anoikis resistance, proliferation, migration, invasion, and EMT." (PMID 35589677, 2022). "We orthogonally confirmed recruitment of the key adaptor, GRB2, to endogenous EML4-ALK cytoplasmic protein granules detected by IF in patient-derived cancer cells (H3122), as well as through dual expression of EML4-ALK and GRB2 in Beas2B cells." (PMID 33848463, 2021). "In contrast, accumulating evidence reveal that PSMD14 also suppress the ubiquitination and degradation of specific proteins, such as SNAIL 37, GRB2 38 and ALK2 receptor 39, to promote cancer progression." (PMID 33456565, 2021). "After dividing dogs into groups according to breed we found upregulation of RAC1 together with GRB2 and CDH1 in carcinoma-solid compared to carcinoma-simple in mixed-breed dogs." (PMID 34679042, 2021). "These discoveries are integral in shaping the era of targeted cancer therapy, with direct targeting of RAS or downstream RAS effectors, such as Grb2 and MAPK a possibility." (PMID 32257368, 2020).
cancer (continued). "A study showed that N-cadherin induces EMT and cancer stem cell-like characteristics through activating the ErbB pathway by upregulating ERK, growth factor receptor-bound protein 2 (GRB2), and SHC-transforming protein." (PMID 33142749, 2020). "The subgroups include proliferation genes (Ki67, STK15; Survivin, CCNB1, MYBL2), invasion genes (MMPP11, CTSL2), HER2 genes (GRB2, HER2), estrogen genes (ER, PGR, BCL2, SCUBE2), and other cancer related genes (GSTM1, CD68, BAG1)." (PMID 33665165, 2020). "Other noteworthy mechanisms promoting cancer cell migration include EGFR downstream activator son of sevenless (SOS) and growth factor receptor-bound protein 2 (GRB2) that increases PI3K-AKT signaling." (PMID 29478325, 2019). "A comprehensive understanding of the binding between Gab2503-524 and Grb2 SH3C, a crucial interaction in normal cellular signalling for a number of cancer conditions, demands the full description of their mechanism of recognition." (PMID 29137268, 2017). "Lastly, our method not only identified the known cancer genes but also detected the potential rare drivers (PTPN6 in THCA, SRC, GRB2 and PTPN6 in KIRC, MAPK1 and SMAD2 in HNSC)." (PMID 28938536, 2017). "In contrast to findings of other blood-based studies, we found at least four NSCLC-associated markers that were involved in Ras/MAP kinase and cell growth control pathways highly relevant to cancer: DUSP6, GRB2, MDM2, and NF1." (PMID 27418131, 2016). "Proteins known to be involved in growth signals, thus leading to self-sufficiency in cancer cells, such as TGFBR1, EGFR, IGFR1R, GRB2, are in the ‘hubs’ of CGN." (PMID 23166660, 2012). "It appears in the mammalian Grb2-Ras signaling pathway with SH2/SH3 domain interactions and several functions in embryogenesis and cancer." (PMID 22034985, 2011). "The log fold changes and, thus, the rankings among all the DEGs are almost the same for each of the found key genes ITGA2B, FLNA, GRB2, FCGR2A, and APP across all three datasets, confirming that these are consistently differentially expressed in NSCLC vs. healthy/non-cancer." (PMID 41226816, 2025). "Interestingly, when comparing malignant colon tissues with normal tissues, an increase in the relative expression of GRB2 and a relatively low expression of GRB3-3 can be observed in cancer samples." (PMID 38540680, 2024). "In addition, the compound reduced the expression of proteins involved in cancer cell migration and invasion, such as PKC, GRB2, Rac, Rho A, Ras, MKK7, and MEKK3." (PMID 38374934, 2024). "In accordance with our hypothesis, several previous studies indicated Grb2 as an essential component in the regulation of MAPK signaling, namely downregulation of Grb2 expression, reduced MAPK activation and impaired cancer cell survival." (PMID 38286037, 2024). "We hypothesize that our observed NRas-BRAF clusters and the NRas interactions with Grb2, NF1, and GPI in clusters could serve as novel targets for cancer therapy." (PMID 36304112, 2022). "Similarly, Grb2-mediated PI3K signaling cascade plays a critical role in the proliferation and migration of cancer cells." (PMID 35589677, 2022). "The anti-cancer effect of THSWD might by achieved via the down-regulation of MAPK1, HRAS, GRB2, AKT1, and MAPK14." (PMID 34513708, 2021). "Furthermore, the phosphorylation levels of EGFR, ERBB2, GRB2, and SRC were significantly reduced in the PAF-AH 1B2 KD cancer cells as determined by the Luminex assay and western blot data." (PMID 34930255, 2021). "The role of upregulation of non-phosphorylated Shp2 through binding to monomeric Grb2 in cancer has not previously been investigated." (PMID 33795832, 2021). "As GRB2 has been suggested to be a therapeutic target for cancers by targeting its SH2/SH3 domains, it may be interesting to further study the synergistic anticancer effect of GRB2 and NSUN2-mediated m5C modification in ESCC." (PMID 34345012, 2021). "We found that GRB2 and RAC1 gene expression levels were increased in the III grade carcinomas." (PMID 34679042, 2021).
cancer (continued). "In addition, the interactions among GRB2, EGFR, HIF1A, and SLC2A1 were also highly correlated with cancer in the KEGG “Pathways in cancer” (pathway #5200)." (PMID 32170141, 2020). "Our previous studies showed that F806 suppresses cancer progression; though it downregulates the protein expression of actin cytoskeleton linkers ITGB1 and GRB2, proteins are involved in the formation of focal adhesions, which implies F806 can control dynamic changes of the cytoskeleton." (PMID 30327774, 2018). "Using binding assays, protein complementation and phenotypic readouts to characterize the pY-dependent interactions of TSPAN2 (tetraspanin 2) and GRB2 or PIK3R3 (p55γ), we exemplarily provide evidence that the two pY-dependent PPIs dictate cellular cancer phenotypes." (PMID 25814554, 2015). "The hypothesis is that conditional pY-dependent interactions with different adaptor proteins, GRB2 or PIK3R3, respectively, may be altered in cancer, suggesting further investigation of TSPAN2 and its interactions in the transition of cells to abnormal growth." (PMID 25814554, 2015). "To date, no studies have reported on spontaneous antibodies to GRB2 in cancer patients." (PMID 39086481, 2024). "We further investigated how 4-carbomethoxyl-10-epigyrosanoldie E impacts the levels of proteins such as FAK, PKC, GRB2, Rac, Ras, RhoA, MEKK3, and MKK7, which are upstream regulators in the MAPK pathway and play a role in controlling the expression of MMPs involved in cancer cell metastasis." (PMID 38374934, 2024). "Therefore, the Grb2-SH2 domain and Gab1-MBD motif might function as epitope peptides to block the interaction of endogenous Grb2 or Gab1 with c-MET, thereby limiting the proliferation of cancer cells." (PMID 36233320, 2022). "Ultimately, Grb2, which mediates RTKs and SOS, is the only protein that has been identified in the MAPK signaling pathway, which indicates the MAPK signaling pathway may play a less significant role in cancer signal transduction than the PI3K/Akt pathway." (PMID 29297291, 2017). "Furthermore, since PI3K integrates both the ErbB2/Grb2/SOS/RAS and ErbB3/p85 pathway, the ErbB2-overexpressing cancer cells become addicted to the PI3K signalling hub, as manifested by increased susceptibility to PI3K inhibitors, compared with ErbB3 inhibition." (PMID 27255951, 2016). "An intriguing side effect of Grb2 phosphorylation as a potential negative regulator is that tyrosine kinase inhibitors, such as those widely used as cancer therapeutics in EGFR-driven cancers, could also inhibit this negative regulatory mechanism—conceivably interfering with their desired effects." (PMID 35507881, 2022). "In addition, phosphorylation of Tyr925 was reported to induce the generation of growth factor receptor-bound protein 2 (GRB2) binding site for GRB2, which activated the Rasmitogen-activated protein kinase signaling cascade to promote focal contact turnover and contribute to cancer cell migration." (PMID 26004127, 2015). "Although ATXN1, SMAD9, UBQLN4 and GRB2 are not included in CGC, we have already mentioned that ATXN1, SMAD9 and UBQLN4 are all relate to cancers or pathway in the last paragraph." (PMID 31888623, 2019). "However, overexpression of miR-4516 did not influence TGF-β2-induced expression of SOX4, GRB2, and ETV4 in ARPE cells, although previous studies have reported that SOX4, GRB2, and ETV4 contribute to EMT in cancer cells." (PMID 35771766, 2022). "For example, the following top 100 MDS genes can be mentioned that are not yet covered by approved or experimental cancer or antineoplastic drugs [according to DrugBank, DGIdb, FDA6, HMDB, Tocris7, GeneCards databases]: GRB2, SOS1,SOS2, SHC1, GNB1, CREB1, GNG2, GNAQ, GNB5, GNAI2." (PMID 30728774, 2019).
tumor (122 papers, 2005 to 2025). "In ovo studies in a CAM (Chicken Chorioallantoic Membrane) model indicated that GRB2 knockdown, as well as overexpression of GRB2 loss-of-function mutants (Y52A and S86A-R88A) compromised tumor growth." (PMID 38182563, 2024). "Another study also showed that miR-376c was regulated by DNA methylation and associated with tumor suppression by targeting growth factor receptor-bound protein 2 (GRB2)." (PMID 32998289, 2020). "Here, we demonstrate that in two independent Theileria-transformed macrophage cell lines Grb2 expression is down-regulated concomitant with loss of tumor virulence." (PMID 26511382, 2015). "In particular, tumor cells with oncogenic replication stress might select for GRB2 activities associated with proliferation and the DDR." (PMID 38459011, 2024). "Furthermore, expression of GRB2 gene is associated with the grade of tumor in mixed breed dogs (p = 0.039): the III grade tumors had the higher expression than the I grade tumors." (PMID 34679042, 2021). "Among them, EGFR(7p11.2), TWIST1(7p21.2), RAC1(7p22), MTDH(8q22.1), CCNE2(8q22.1), TNFRSF11B(8q24) and GRB2(17q25) might be good candidates, as they are reportedly associated with invasiveness and metastasis of tumor cells." (PMID 23457519, 2013). "Moreover, Grb2 is associated with β1 integrin and overexpressed in various tumor entities." (PMID 38286037, 2024). "The data revealed that tumor growth was severely retarded in the Tra treatment group with decreased protein levels of pMek, pErk, Kras, and Grb2." (PMID 40157910, 2025). "IHC staining of GRB2 showed that the expression of GRB2 was higher in the HCC section than in the para‐tumour section." (PMID 40831000, 2025). "Subsequently, phosphorylated ENO1 is linked to the SH2 domain of GRB2 protein, thereby activating the downstream MAPK signaling pathway and triggering tumor proliferation." (PMID 39563492, 2025). "Subcutaneous xenograft nude mouse model showed that DDX42 significantly promoted tumour growth as compared to the control group and lifted the expression of GRB2, KI‐67 and PCNA in vivo." (PMID 40831000, 2025). "We conducted a comprehensive bioinformatic analysis to investigate the mRNA and protein expression levels of Tks4 and its associated partner molecules (CD2AP, GRB2, WASL, SRC, CTTN, and CAPZA1) across different tumor types." (PMID 39234565, 2024). "A mutant Shc protein that replaces Tyr317 with Phe loses its ability to be highly phosphorylated at tyrosine, bind to GRB2, and induce tumor transformation when activated by growth factor receptors." (PMID 38540680, 2024). "Consistent with the augmentation of tumour suppressor let-7 miRNA, GRB2 knockout inhibited expression of pro-oncogenic miRNA families mir-17, mir-19 and mir-221." (PMID 37328606, 2023). "CAPZA1, HLA-E, IMPA2, NFE2L3, PLEKHO1, SIGLEC1, and UBE2Z were expressed at higher levels in tumor tissues, whereas EMX2, FGL2, FUCA1, and GRB2 were expressed at lower levels in tumor tissues." (PMID 35127943, 2022). "The Grb2 splice variant Grb3-3 results in decreased activation of the Ras-MAPK pathway due competition with Grb2 for SOS binding, with reduced Grb3-3 levels observed in tumour tissue suggestive of a mechanism for enhancing Ras pathway activity." (PMID 36171279, 2022). "In tumour cells, expression of hnRNPC is reduced, therefore exon 4 is included resulting in elevated levels of Grb2 and reduced expression of the negative regulator Grb3-3." (PMID 36171279, 2022). "IM directly inhibits the substrate such as; GRB2 (Growth Factor Receptor Bound Protein 2) from entering the tyrosine kinase site, leading to the prevention of tumor cell proliferation." (PMID 36078884, 2022).